ZNF285CP (zinc finger protein 285C, pseudogene)
Synonyms: formerly ZNF806
Gene: Transcribed unprocessed pseudogene on chromosome 2 (132,309,309 to 132,318,736, forward strand). Ensembl gene ENSG00000018607.
Diseases named in the same sentence as ZNF285CP in open-access papers:
ZNF285CP is named in the same sentence as 3 diseases in open-access papers, as found by Europe PMC text mining. Sharing a sentence is not in itself a finding about the gene and the disease.
ZNF285CP shares sentences with these, for which no sentence is quoted: Alzheimer disease (1 paper); glioblastoma (1); tumor (1).